LYZ (lysozyme)
Diseases named in the same sentence as LYZ in open-access papers (continued):
Sharing a sentence is not in itself a finding about the gene and the disease.
infection (continued). "Plasma lysozyme is a simple and commonly used marker of innate immune competence in fish, as response to vaccination, infection and immunosuppression." (PMID 28462060, 2017). "Overall, the infection of isolates B6884 and M9374 significantly enhanced the expression of all studied effectors, particularly Defensin-like protein, C-type lysozyme, and Thaumatin-like protein." (PMID 27618036, 2016). "As the first line of defence, various peptides such as lysozyme, antibodies, and complement factors inhibit the adhesion and colonization of microorganisms, leading to the prevention of infection and disease." (PMID 27294156, 2016). "Previous studies have shown that the intelectin 2 plays an important role in expel intestine parasite infection, and the lysozyme participates in host defense against bacterial infection." (PMID 26252489, 2015). "We further found that transcription of lysozyme-coding genes was also altered after infection with the pathogens." (PMID 26162375, 2015). "For example, the S. pneumoniae pdgA mutant (with a nonfunctional pdgA gene) developed hypersensitivity to exogenous lysozyme and decreased virulence in a mouse infection model." (PMID 24975018, 2014). "The lysozyme activity has been found to be modulated by a range of factors including stress, water temperature, infection of foreign materials, nutrients etc.." (PMID 25405077, 2014). "Shrimp surviving 84 hours post-infection have higher expression of lysozyme, C-type lectin, penaeidins, prophenoloxidase-1 and prophenoloxidase-2 in haemocytes than those dying less than 60 hours post infection." (PMID 25164406, 2014). "After 10th day of infection, the serum lysozyme activity was decreased and the least serum lysozyme activity of 4.55 ± 0.241 μg/ml was observed in the control fish on the 20th day after infection." (PMID 25405077, 2014). "Shrimp lysozyme has been shown to be effective in blocking infection by WSSV in blue shrimp (Litopenaeus stylirostris)." (PMID 25164406, 2014). "Animals surviving 84 hours post-infection with White Spot Syndrome Virus (WSSV) have higher expression of lysozyme, C-type lectin, penaeidins, prophenoloxidase-1 and prophenoloxidase-2 in haemocytes than those dying less than 60 hours post-infection." (PMID 24465553, 2014). "Lysozyme, cathepsin D, a nitrophorin-like protein and a putative 14 kDa protein were significantly upregulated upon infection, whereas thioredoxin reductase was downregulated." (PMID 23658688, 2013). "For successful establishment of mucosal colonization and for deeper infection S. aureus must be able to survive attack by a variety of potent antimicrobial substances, including reactive oxygen and nitrogen species, lysozyme, defensins and cathepsins." (PMID 24130480, 2013). "Levels of lysozyme rose rapidly three to six days after the inoculation to ten to twenty than their pre- infection levels." (PMID 23323096, 2012). "Plasma lysozyme levels were thus well high after the rodents had their parasitaemias (7 to 13 days after infection in Microtus, Clethrionomys and Apodemus, BK rats 6- 12 weeks and in mice 3- 4 weeks." (PMID 23323096, 2012). "Following the peak in activity during the first week of infection lysozyme levels fell but remained 2 to 10 times higher than control values for at least one year when the highest level was in mice, infected with T. grosi." (PMID 23323096, 2012). "The lys-1 lysozyme is an antimicrobial peptidoglycan N-acetylmuramoylhydrolase that has been shown to protect against infection in C. elegans." (PMID 21209831, 2010). "In contrast to this, the N'Dama showed an initial 2.8-fold increase (P = 0.0286) in LYZ mRNA abundance at 14 dpi relative to pre-infection that was followed by later decreases in expression." (PMID 19409086, 2009). "Conversely, significant down-regulation of lysozyme gene was also observed at 48 h and 72 h post infection (p<0.05)." (PMID 19806192, 2009).
infection (continued). "We observed a 13-fold increase of lysozyme in PL-Lab infections (p < 0.01) and a 16-fold increase of hymenoptaecin but there were too few peptides detected for apidaecin 22 and defensin to meet our criteria for quantitation." (PMID 19695106, 2009). "Experiments are currently underway with over-expressing lysozyme M mice to see if these transgenic mice are more resistant to infection." (PMID 18842154, 2008). "Indeed, toxin-dependent increases in lysozyme relative to that contained in serum significantly inhibited infection." (PMID 41326716, 2026). "Thus, lysozyme can counteract Salmonella in two ways: (i) inhibiting intracellular infection, and (ii) dampening toxin-induced oxidative stress and resulting DDRs." (PMID 41326716, 2026). "Lysozyme, a marker of activated macrophages, was detected in all infected animals and showed significantly higher expression during the convalescent phase of secondary infection (SI) (p < 0.01)." (PMID 41472288, 2025). "Third, during pathogen infection, lysozyme is rerouted into the secretory autophagy pathway, and it is unknown how this alternate trafficking integrates with microbiota-enhanced translation." (PMID 40832175, 2025). "However, intestinal invasion by enteric pathogens, such as S. Typhimurium, significantly suppresses lysozyme expression, exacerbating infection and inflammation." (PMID 40242449, 2025). "The time course of infection was then followed by evaluating positivity to V. ostreicida by PCR, responses of haemolymph components (haemocyte lysosomal membrane stability and serum lysozyme activity) and tissue histopathology (gills and digestive gland)." (PMID 41383590, 2025). "The LYZ level responds to infection, stress, and nutritional factors." (PMID 40163232, 2025). "Therefore, there are many studies related to the use of lysozyme in the treatment of traumatic infections and skin diseases." (PMID 40283196, 2025). "Moreover, in many insects, including A. mellifera, an expression of lysozyme genes is induced upon systemic infection and after injection of cell wall components of bacteria and fungi." (PMID 39813262, 2025). "The chromatographic screening for proteins and peptides whose level changes after infection with P. entomophila identified the presence of proline-rich peptide 1 and 2, a cecropin D-like peptide, galiomycin, lysozyme, anionic peptide 1, a defensin-like peptide, and a 27 kDa hemolymph protein." (PMID 40019037, 2025). "Immunoblots showed an increase in the intensity of antibody recognition of Nf lysozyme, suggesting an active involvement of this protein in the interaction with some bacteria and with mammalian cells, which could have an impact on the infection of the host." (PMID 40096149, 2025). "C3 and LYZ have a substantial role in the innate immune function of fish against infection." (PMID 38561720, 2024). "We found that infection reduced the lysozyme expression in Paneth cells at protein and RNA levels." (PMID 38823640, 2024). "Post-infection, dietary Glut and 1% omega-3 increased intestinal interleukin-10 (IL) and secretory immunoglobulin-A and serum lysozyme, while decreased the elevated inflammatory mediators comprising interleukin IL-6, tumor necrosis factor-alpha, nitric oxide (NO) and inducible NO synthase." (PMID 38961536, 2024). "Always using the MNV-1 mouse norovirus model, the containment of food infection by lysozyme was also demonstrated in some bread fillings, where treatment with the heat-denatured lysozyme immediately after MNV-1 inoculation completely eliminated viral contamination." (PMID 38338396, 2024). "An interesting paper on the antibacterial activity of lysozyme comes from Ragland and Criss who emphasized the crucial role of this enzyme in the so-called natural immunity and its fascinating function as an immunomodulator for coping with infections." (PMID 38338396, 2024).
infection (continued). "However, there was a significant increase in the activity of SOD and lysozyme (LZM) within the initial 12 hours following infection (P < 0.05)." (PMID 39760091, 2024). "In addition, the heterologous expression of lysozyme was reported to reduce infection by Pectobacteria." (PMID 37630640, 2023). "Upregulation of lysozyme expression in response to a systemic infection indicates either a putative role of the hematopoietic organs in the humoral defense by secreting lysozyme or an increased hemocyte maturation, forming more immune competent cells (plasmatocytes) in response to an infection." (PMID 37900309, 2023). "Lysozyme plays a role in the protection of turtle eggs from infection." (PMID 36830343, 2023). "CXCL1, IP-10, IL-8, lysozyme and lactoferrin were longitudinally profiled over the course of infection in a Gambian cohort study, with evidence of an inflammatory response both before, during and after detectable infection." (PMID 37862368, 2023). "Lysozyme activity in the hemolymph of bacteria-injected larvae increased 4h post-infection." (PMID 36689436, 2023). "At 21 DPC, lysozyme activity dramatically decreased, indicating downregulation of the innate immune components and further suggesting that surviving fish have cleared the infection." (PMID 36986384, 2023). "CXCL1, IP-10, IL-8, lysozyme and lactoferrin were longitudinally profiled over the course of infection in a separate cohort, with evidence of an inflammatory response both before and after detectable infection." (PMID 37862368, 2023). "For example, expression of the lysozyme-encoding C. elegans genes lys-1, lys-7 and lys-8 is augmented during infection with the Gram-negative Serratia marcescens." (PMID 36184586, 2022). "Moreover, we investigated alterations in phagocytic capacity, cellular agglutination, and lysozyme contents in A. japonicus after infection with V. splendidus." (PMID 35911684, 2022). "Furthermore, utilizing lysozyme conjugates with galactomannan or palmitic acid as a therapeutic for infection in fish, the survival rate was increased after supplementing the dietary lysozyme to the Edwardsiella tarda-infected carp, Cyprinus carpio L.." (PMID 37073222, 2022). "In fish, lysozyme expression changes in different tissues to cope with pathogen infection." (PMID 36551460, 2022). "Strikingly, we observed a significant reduction of A. laibachii colonization in leaves treated with the active GH25 lysozyme, while the mutated enzyme GH25_D124E did not significantly influence infection (p-value of <0.0001 and an R2 value of 98.88%)." (PMID 33427195, 2021). "In this study, only lysozyme in CL1 was found to be notably up-regulated in secondary infection." (PMID 34295333, 2021). "A temporally limited increase in mRNA levels was registered in hemocytes, indicating that circulating cells are the main source of lysozyme production during infection and their synthesizing activity is needed to maintain high levels of lysozyme in the hemolymph." (PMID 34867970, 2021). "In addition to its direct bactericidal activity, recent evidence has shown that lysozyme mediated bacterial lysates can modulate the innate immune response against pathogen infection by activating pattern-recognition receptors or the complement system." (PMID 34946096, 2021). "Transgenic swine expressing rhLys were generated by a somatic cell transfer, with the aim to feed piglets with the human lysozyme to avoid pathogenic infections and, hence, a negative impact on neonatal survival." (PMID 34943746, 2021). "This shows that CC3 Chinese isolates may have lost the crucial genes related to lysozyme, and antimicrobials, which might be trapped by the host defense mechanism during the infection process." (PMID 34778102, 2021).
infection (continued). "In addition, some immune effector factors including cytochrome P450 1B1-like, glutathione S-transferase 6, monomeric sarcosine oxidase, low affinity immunoglobulin epsilon Fc receptor, and lysozyme were also increased in the second infection." (PMID 34295333, 2021). "It was proved that the lack of lysozyme M and P significantly increase the susceptibility to respiratory tract infection, especially the infection related to the colonization of Gram (+)." (PMID 34925025, 2021). "In several bacterial pathogens, modifications that render PG resistance to lysozyme support the ability to establish infections, and at least two different mechanisms may explain this." (PMID 34721369, 2021). "Lysozyme in fish could also be acting as an acute-phase protein involved in the overall alarm response to pathogen infection." (PMID 33187217, 2020). "The ileum, after infection with the AvrA present strain, contained an increased proportion of Paneth cells with disorganized or diminished granules or exhibited diffuse cytoplasmic lysozyme staining." (PMID 32362899, 2020). "The aim of the study was to evaluate the dynamics of myeloperoxidase (MPO) and lysozyme (LZM) in the experimental infection of rabbits with the Lagovirus europaeus/GI.1a virus, which is a pathogen causing high mortality, decimating rabbit farms all over the world in a short time." (PMID 32899838, 2020). "Additionally, on 7, 49 days post-vaccination and post-infection with A. hydrophila, lysozyme activity were significantly higher in fish vaccinated by BF, followed by MA vaccinations." (PMID 32615969, 2020). "After IVA infection, the volume density of TNFα-positive cells increased 2.3-fold compared to the healthy control and constituted 32.2% ± 4.7%, and the numerical density of lysozyme-positive cells decreased 2.3-fold and constituted 11.1 ± 0.6." (PMID 32937880, 2020). "Considering the possibility that lysozyme concentrated in the scar-region diffuses to equally distribute over the cell membrane, lysozyme scars on J774A.1 cells were monitored as a function of time after infection." (PMID 34737689, 2020). "Post infection, all the groups had increased lysozyme activity." (PMID 30988331, 2019). "Additionally, the interaction of both factors (diet and infection) evidenced that seabass fed the CTRL diet had lower lysozyme activity (p = 0.005) than fish fed GRA diet." (PMID 31695116, 2019). "Similarly, the transcription level of AMP genes, including attacin, cecropin, and lysozyme, were greatly up-regulated following the infection of E. coli and S. aureus, but they decreased when endogenous PGRP-SA was knocked down in A. pernyi." (PMID 30893923, 2019). "Finally, our studies involving lysozyme defective mice further support SliC as a critical inhibitor of lysozyme during infection." (PMID 29975784, 2018). "Moreover, fish fed the CTRL dietary treatment showed higher lysozyme concentration at 48 h than at 0 and 4 h after infection, while fish fed MET 0.5 and MET 1 presented higher values at 24 h than at 4 or 0 and 4 h, respectively." (PMID 30524433, 2018). "Besides blood profiles, the phagocytic index, respiratory burst and lysozyme activity are good indicators for immunological status of fish during infection periods." (PMID 30984371, 2018). "NGO1063 displays low overall sequence similarity to the MliC/PliC protein family, but we demonstrate that it has a parallel inhibitory mechanism and provide the first evidence that the conserved residues involved in lysozyme inhibition are functionally critical during in vivo infection." (PMID 29975784, 2018). "This may be explained by the significantly higher levels of lysozyme and IgY in the eggs of great tits, protecting the embryo from increased infection pressure." (PMID 30286089, 2018). "One lysozyme CDS was induced by infection in both A. sculptum and A. aureolatum." (PMID 28503490, 2017).
infection (continued). "In addition to its direct antimicrobial role, more recent evidence has shown that lysozyme modulates the host immune response to infection." (PMID 28934357, 2017). "This review will highlight recent advances in our understanding of the diverse mechanisms that bacteria use to protect themselves against lysozyme, the intriguing immunomodulatory function of lysozyme, and the relationship between these features in the context of infection." (PMID 28934357, 2017). "Expression of lysozyme inhibitors likely contributes to bacterial colonization and infection." (PMID 28662181, 2017). "While these observations indicate that O-acetylation is important for bacterial physiology as well as in resistance to lysozyme, the interplay between these functions in the context of infection remains unclear." (PMID 28934357, 2017). "Besides, in vivo experiments confirmed that lysozyme can help pigs to recover from diarrhea after infection with E. coli." (PMID 25955256, 2015). "Moreover, IL-15 and lysozyme are secreted by macrophages and recruited to sites of infection to clear pathogens." (PMID 26572495, 2015). "Notably, the kinetics of IL-9 response in this infection model fits that observed in a hen egg lysozyme (HEL) immunization model, showing peaks of IL-9 at day 3 and subsequent sharp decline." (PMID 25646821, 2015). "For the subset of down-regulated genes that respond to the resolution of the infection, the 2 top-scoring GO clusters, c-type lectins and lysozyme groupings, have previously been described as part of an inducible C. elegans immune response to a variety of pathogens." (PMID 25340560, 2014). "Regarding the role of the enhanced antimicrobial activity recorded for the T. cruzi Dm28c-infected R. prolixus, triatomine vectors have been shown to produce endogenous antimicrobial peptides (defensin and lysozyme) in the gut/fat body following infection with T. cruzi or bacteria." (PMID 22574189, 2012). "Thus, infection by P. aeruginosa likely induced the expression of lysozyme, which was subsequently degraded by LasB and other exoproteases produced by PAO1 or PDO240lasB." (PMID 22069491, 2011). "However, significant down-regulation of lysozyme was observed only at 6 h for BALB/c mice (p<0.05) while up-regulation of SLPI was observed only at 24 h post infection in BALB/c mice (p<0.05)." (PMID 19806192, 2009). "The second explanation could be linked to the bioactive compounds found in whey, such as immunoglobulins, α-lactalbumin, β-lactoglobulin, lactoferrin, hormones, growth factors, and lysozyme, which have multiple positive health effects, including preventing inflammation, infection, and cancer." (PMID 40458758, 2025). "We have identified three promising candidate virulence factors, namely lysozyme, cystatin and hemerythrin, which may be critical in facilitating N. fowleri evasion of host defenses, migration to the brain and induction of a lethal infection." (PMID 40096149, 2025). "Therefore, EMILIN1 and LYZ may be closely related to the pathogenesis of BD and the regulation of infection and inflammation, potentially playing positive and active anti-inflammatory roles." (PMID 39687011, 2024). "We speculated that application of exogenous lysozyme might be more efficient than endogenous lysozyme possibly by distinct trafficking or simply by increasing the bio-active concentration at the site of infection." (PMID 38900248, 2024). "Hence, the enhancement of plasma lysozyme and complement activities by dietary phytol may prove advantageous in safeguarding the fish against subsequent infections, as evidenced by previous studies on other feed additives." (PMID 39555567, 2024). "Certain immune-relevant proteins and peptides, including lysozyme, apolipophorins, and anionic peptides, are normally present in the hemolymph of healthy larvae and their concentration could be altered after pathogen infection." (PMID 36689436, 2023).